SNHG6 (small nucleolar RNA host gene 6)
Diseases named in the same sentence as SNHG6 in open-access papers (continued):
Sharing a sentence is not in itself a finding about the gene and the disease.
cancer (continued). "Previous studies have elucidated the oncogenic role of small nucleolar RNA host gene 6 (SNHG6) in some types of human cancers, whereas it is unclear whether it functions as an oncogene in CC." (PMID 32884447, 2020). "Additionally, the subsequent application of SNHG6 as a prognostic indicator in the routine clinical guidance of cancers deserves further exploration." (PMID 32000704, 2020). "Therefore, further studies are required to fully appreciate the functions of SNHG6 in the progression of cancers." (PMID 32321469, 2020). "Collectively, our meta-analysis preliminarily suggests that SNHG6 could serve as a potential biomarker for predicting prognosis and clinical features in patients with multiple types of cancer." (PMID 32000704, 2020). "Fourth, it should be taken into account that variation in therapeutic regimens and cut-off definitions might result in an impact on survival outcomes and an overestimate of the prognostic significance of SNHG6 in human cancers." (PMID 32000704, 2020). "Currently, despite diverse articles that unveil the link between SNHG6 and cancers, the prognostic value remains contradictory or inconclusive, which may be attributed to limited sample size and methodology." (PMID 32000704, 2020). "Thirdly, most of the HRs and 95% CIs were calculated indirectly based on the survival curve, which might result in the overestimation or underestimation of the clinical significance of SNHG6 expression in many cancers." (PMID 32321469, 2020). "In terms of mechanism, we found that SNHG6 could act as a molecular sponge of miR-26a, miR-26b, and miR-214 in the cytoplasm and exert its cancer-promoting effects by regulating EZH2, a common target of these microRNAs." (PMID 30626446, 2019). "Small nucleolar RNA host gene 6 (SNHG6) regulates diverse biological processes in cancers." (PMID 31533634, 2019). "A previous study confirmed that SNHG6 aberrantly expressed in human would result in cancer." (PMID 28938549, 2017). "The study concluded that suppressing SNHG6 could inhibit cancer cell proliferation and encourage apoptosis in NSCLC cells; this anti-cancer effect was found to be mediated through the regulation of p21, a protein involved in cell cycle regulation and apoptosis." (PMID 37735423, 2023). "Finally, SNHG6 was indicated in the meta-analysis as an oncogene connected with cancer progression and could be used as a promising prognostic biomarker." (PMID 32947877, 2020). "Mechanistically, SNHG6 induces hnRNPA1 to bind and splice PKM transcript in CRC cells, hence, sensitizing cancer cells for aerobic glycolysis sensitizing cancer cells for aerobic glycolysis." (PMID 37735423, 2023). "Experiments showed that overexpression of SNHG6 in ovarian cancer cell lines SKOV3 and A2780 significantly boosted cancer cell proliferation, migration, invasion, and EMT." (PMID 37735423, 2023). "SNHG6 binds to miR-944 and miR-181d-5p leading to an increase in ETS1 expression eventually accelerating cancer cell proliferation, EMT, and inhibiting apoptosis." (PMID 37735423, 2023). "Among the ceRNAs of miR-944, highly expressed circSERPINA3, circHAS2, SNHG6, and PRNCR1 can be used as biomarkers for poor clinicopathological features and poor prognosis in cancer patients." (PMID 36077769, 2022). "Therefore, SNHG6 may potentially be used as a novel prognostic biomarker in human cancers." (PMID 32321469, 2020). "Thus, SNHG6 might serve as a biomarker for cancer diagnosis and prognosis." (PMID 32518528, 2020). "Accumulating data demonstrates that SNHG6 can induce EMT in cancer cells via targeting EMT-TFs such as TGF-β and ZEB1, making it an efficient target in suppressing metastasis of cancer cells." (PMID 32784711, 2020). "Dysregulation of small nucleolar RNA host gene 6 (SNHG6) exerts critical oncogenic effects and facilitates tumourigenesis in human cancers." (PMID 31119871, 2019).
cancer (continued). "In HCC, SNHG6 upregulates ZEB1 expression by binding miR-101-3p and, in combination with downregulation of Smad7, induces epithelial–mesenchymal transition, speeding up cancer-cell metastasis." (PMID 40636922, 2023). "In this study, we focused on lncRNA SNHG6 which plays a role in chemoresistance of cancer cells, but has never been investigated in the context of tamoxifen resistance." (PMID 36212408, 2022). "SnoRNA host gene 6 (SNHG6) is believed to be involved in several human cancers, but the specific molecular mechanism of SNHG6 in HCC is not well studied." (PMID 33663502, 2021). "An increasing number of studies have demonstrated that the expression of lncRNA small nucleolar RNA host gene 6 (SNHG6) has significantly negative correlation with various cancer prognosis." (PMID 32655318, 2020). "According to recent studies, SNHG6 is overexpressed in cancer tissues compared with the corresponding noncancerous tissues as well as in different cancer cell lines." (PMID 32518528, 2020). "Subsequently, we comprehensively analyzed the effects of SNHG6 on overall survival (OS), DSS, disease-free interval (DFI), and progression-free interval (PFI) of cancer patients, and the results showed that upregulation of SNHG6 may be detrimental to the prognosis of KIRP patients." (PMID 37004005, 2023). "Considering that hnRNPA1 can perform the variable splicing of PKM mRNA in order to increase the ratio of PKM2/PKM1 to promote cancer, the interaction with hnRNPA1 to splice the mRNA of PKM may be an important mechanism of SNHG6 that is involved in the metabolic process of CRC." (PMID 32296635, 2020). "As the coupling effect of SNHG6 was investigated in cancer cells, cholesterol availability sensed by FAF2 was hypothesized to crosstalk with LARS1, which senses leucine availability, in turn activating mTORC1 for downstream signaling pathway activation in diseased states, such as cancer." (PMID 37258576, 2023).
digestive system cancer (2 papers, 2020). A primary or metastatic malignant neoplasm involving any part of the digestive system. "Subgroup analysis indicated a significant association between high SNHG6 expression and shorter OS in those studies with digestive system cancers (HR = 2.05, 95% CI: 1.47–2.62), or with sample size < 70 (HR = 2.70, 95% CI: 1.29–4.11), or with multivariate analysis (HR = 2.04, 95% CI: 1.44–2.64)." (PMID 32321469, 2020).
infection (1 paper, 2023). The state of being infected such as from the introduction of a foreign agent such as serum, vaccine, antigenic substance or organism. "Consistent with previous studies of immune response upon infection, SNHG6 and LINC00861 were upregulated." (PMID 37391481, 2023).
SNHG6 also shares sentences with these, for which no sentence is quoted: liver cancer (4 papers); oesophageal cancer (3); colon adenocarcinoma (2); melanoma (2); breast invasive carcinoma (1); cervical tumour (1); colorectal adenocarcinoma (1); head and neck squamous cell carcinoma (1); oropharyngeal squamous cell carcinoma (1); pituitary adenoma (1); pituitary tumor (1); pulmonary fibrosis (1); renal carcinoma (1); renal fibrosis (1); Stroke (1); ventricular septal defect (1).